CRP (C-reactive protein)
Diseases named in the same sentence as CRP in open-access papers (continued):
Sharing a sentence is not in itself a finding about the gene and the disease.
cardiovascular disease (continued). "Chronic use of the oral contraceptive pill (OCP) is reported to increase C‐reactive protein (CRP) levels and increase the risk of cardiovascular disease in premenopausal females." (PMID 37487629, 2023). "Over the last decade, research in elite athletes and healthy recreationally active female cohorts have consistently demonstrated an intermediate‐to‐high risk of cardiovascular disease (CRP >1 mg L−1) with long‐term oral contraceptive pill (OCP) use." (PMID 37487629, 2023). "A person has a minimal risk of getting cardiovascular disease if their high sensitivity (hs)-CRP level is <1 mg/L." (PMID 38077410, 2023). "A previous studyhas demonstrated a positive association between NLR and hs-CRP levels inindividuals with high risk of cardiovascular disease." (PMID 39076402, 2023). "Serum MMA predicted a 10-year risk of mortality in adults with cardiovascular disease better than CRP." (PMID 38017447, 2023). "CRP is a serological marker of systemic inflammation that has been linked to a higher risk of a number of systemic illnesses, such as cardiovascular diseases and unfavorable pregnancy outcomes (Wu, Trevisan & Genco, 2000; Pitiphot, 2005)." (PMID 38077410, 2023). "In our study, we defined CAR as the ratio of hsCRP to albumin, based on prior research confirming hsCRP as being more strongly associated with cardiovascular disease prognosis than CRP." (PMID 37649485, 2023). "Due to the close associations of body weight and BMI with the inflammatory biomarker and cardiovascular disease risk factor C-reactive protein (CRP), the impact of CRP as a surrogate biomarker for vitamin C requirements was also explored." (PMID 37891943, 2023). "Elevated high‐sensitivity CRP levels are associated with an elevated risk of cardiovascular disease events, and CRP levels are often measured in studies as a metabolic risk marker." (PMID 36939017, 2023). "In contrast, 2 studies of patients with cardiovascular diseases found an inverse association between vitamin D and high-sensitive CRP biomarkers." (PMID 36789936, 2023). "Shift work induced circadian misalignment has also been linked to elevated serum CRP levels, BP, interleukin-6 and tumour necrosis factor-α and increased cardiovascular disease risk." (PMID 37925459, 2023). "In the present study two months post-operative results revealed that only three participants had CRP levels below 1.0 mg/L, leaving 27 subjects with a moderate risk of developing cardiovascular disease." (PMID 38077410, 2023). "CRP is associated with cardiovascular diseases, constituting an independent risk factor and prognosis factor." (PMID 36894998, 2023). "Caúla's research showed that periodontal treatment was effective in reducing inflammatory markers related to the risk for cardiovascular disease in 6 months, such as C-reactive protein, cholesterol, and triglycerides." (PMID 37745126, 2023). "The American Heart Association defined peripheral CRP levels greater than 3 mg/L as “high CRP” and as associated with the greatest risk for cardiovascular disease, relative to CRP levels less than 1 mg/L (low CRP) and between 1 and 3 mg/L (moderate CRP)." (PMID 37049401, 2023). "CRP has been also associated in cardiovascular diseases such as acute heart failure, where the marked elevation of this marker at patient admission is related to higher all-cause, cardiac, and non-cardiac death rates." (PMID 36834166, 2023). "As a matter of fact, the relative risk of developing cardiovascular diseases falls into three major categories, i.e. low, average and high, based on the systemic CRP levels." (PMID 36316604, 2023). "Many studies have discussed the importance of CRP levels in predicting the risk of cardiovascular disorders (CVD)." (PMID 39554800, 2023). "High-sensitivity CRP (hs-CRP) assay can measure lower levels of CRP in the blood and is a reliable predictor of cardiovascular disease risk." (PMID 38024382, 2023).
cardiovascular disease (continued). "Blacks, for whom cardiovascular disease is a leading cause of death, had higher concentrations of IL-6, CRP, and fibrinogen than Whites." (PMID 37623156, 2023). "Further results from systematic review studies showed substantial associations between DTAC and most cardiovascular disease-related risk factors such as fasting glucose, blood pressure, CRP, and high-density lipoprotein cholesterol (HDL-C)." (PMID 37637947, 2023). "Elevated CRP levels are considered to be a risk factor for developing cardiovascular diseases in the general population." (PMID 36316604, 2023). "Currently, a CRP level 2.0 mg/L or more is suggested by the American College of Cardiology/American Heart Association guidelines on cardiovascular disease prevention as a cardiovascular risk factor." (PMID 36768404, 2023). "CRP is an acute-phase protein that is elevated in all inflammatory diseases andis associated with a higher risk of cardiovascular disease." (PMID 39077585, 2023). "A CRP level of more than 10 mg/L is associated with an increased chance of getting life-threatening cardiovascular disease within 10 years." (PMID 37575815, 2023). "In these elite athletes, no naturally menstruating females but nine OCP users were considered high risk for cardiovascular disease (CRP >3 mg L−1)." (PMID 37487629, 2023). "C-reactive protein (hs-CRP) is a biomarker linked to an increased risk of cardiovascular disease when found at elevated levels." (PMID 37881393, 2023). "This increase holds notable clinical significance as CRP over 3 mg/L is associated with high risk for cardiovascular disease." (PMID 38136035, 2023). "Multiples studies in humans have described the regulatory molecular mechanisms controlling CRP gene expression in liver, as well as identified mutations associated with CRP blood levels and cardiovascular disease risk." (PMID 37781386, 2023). "CRP is found in relatively higher concentrations in the myocardium of patients with cardiovascular diseases and is associated with microvessel rarefaction, endothelial cell toxicity and cell apoptosis." (PMID 37484982, 2023). "The current study provides evidence of variations in cardiovascular disease risk, as indicated by CRP levels, in well‐trained females, controlling for the rested state prior to sample collection." (PMID 37487629, 2023). "For biomarkers associated with cardiovascular disease, CRP fell by 78%, LDL-P by 76%, Triglycerides by 70%, and HDL-C rose by 44%." (PMID 37942418, 2023). "CRP is a sensitive marker in systemic inflammation, and chronically elevated values are an independent risk factor for cardiovascular disease in both children and adults." (PMID 37998661, 2023). "The aim of this study was to assess the association between fibrinogen (FIB), interleukin-6 (IL-6), C-reactive protein (CRP) and galectin-3 (Gal-3) and the risk of cardiovascular disease using meta-analysis." (PMID 37485268, 2023). "The American Heart Association (AHA) and the Centers for Disease Control and Prevention (CDC) use serum CRP levels to assess the risk level of cardiovascular diseases." (PMID 38005386, 2023). "hs-CRP is more than 10 times more sensitive than CRP, and assessing hs-CRP levels can help doctors estimate the risk of cardiovascular disease in patients." (PMID 36406928, 2022). "CRP, well-established as a strong predictor of risk of developing cardiovascular disease, is an acute-phase protein produced mainly by hepatocytes in response to inflammatory cascade pathway signaling." (PMID 35334908, 2022). "At baseline, CRP was above the threshold for classifying individuals at high risk for cardiovascular disease." (PMID 36278750, 2022). "The level of C-reactive protein (CRP) in the human body is closely associated with cardiovascular diseases and inflammation." (PMID 36551147, 2022).
cardiovascular disease (continued). "In his study, Ridker proposed thresholds for the risk of cardiovascular diseases as follows: under 1 mg/L of blood CRP is a low risk, 1–3 mg/L is a moderate risk, and a high risk starts at CRP blood levels above 3 mg/L." (PMID 35624645, 2022). "CRP is considered one of the main markers for inflammation, and various cardiovascular diseases are linked to inflammatory processes, contributing to acute cardiovascular events and mortality." (PMID 36307429, 2022). "CRP is a protein produced by the liver under stimulation of pro-inflammatory cytokines, and the hs-CRP assay is a recommended marker of low-grade inflammation for screening the risk of cardiovascular diseases." (PMID 35958257, 2022). "Previous studies have found that social isolation is associated with a high cholesterol response to stress, elevated blood pressure, fibrinogen, and C-reactive protein, which increases the risk of diseases such as cardiovascular disease." (PMID 35480585, 2022). "In the past decades, the role of circulating levels of CRP in the risk of cardiovascular disease and ictus has been established." (PMID 35888682, 2022). "Hypertrophied adipocytes exhibit a distorted cytokine secretion profile; cytokines are key drivers of C-reactive protein (CRP) production, which is associated with cardiovascular diseases (CVD), and a significant predictor of CVDs’ clinical course." (PMID 36088317, 2022). "Inflammation induced by clonal hematopoiesis and immune cell dysfunction thus seems to contribute to the association between CRP increase (i.e., acute-phase reaction) and cardiovascular disease." (PMID 35160156, 2022). "In an apparently healthy population, low risk for cardiovascular disease is defined as CRP <1 mg/L and high risk as >3 mg/L." (PMID 35683538, 2022). "Elevated serum levels of acute-phase proteins such as CRP and fibrinogen, which indicate chronic subclinical inflammation, have been associated with cardiovascular disease." (PMID 35052780, 2022). "Given that CRP actively contributes to the development of atherosclerotic plaque, instability in blood flow, and subsequent clot formation, it is also considered a cardiovascular disease risk factor." (PMID 36381804, 2022). "Elevated serum concentrations (>3 mg/L) of the acute-phase protein, C-reactive protein (CRP), is used as a clinical marker of inflammation and is reported to be a strong risk factor for cardiovascular disease." (PMID 35821205, 2022). "As part of inflammation, elevated CRP is associated with cardiovascular disease, which is well-established by the Centers for Disease Control and the American Heart." (PMID 36105101, 2022). "The sensitivity C-reactive protein (HS-CRP) test is linked to systemic inflammation, and higher levels are linked to an increased risk of cardiovascular disease." (PMID 36264449, 2022). "According to established cut-off values, CRP levels below 1 μg/ml are associated with a low, between 1 and 3 with an intermediate and >3 μg/ml with a high risk for the development of cardiovascular diseases." (PMID 35493955, 2022). "APOE gene variation has been associated with the concentration of C-reactive protein (CRP), a well-established marker of inflammation and an independent risk factor for cardiovascular disease (CVD)." (PMID 36361733, 2022). "CRP is used as a clinical marker of inflammation with elevated serum concentrations (>3 mg/L) shown to be a strong independent risk predictor of cardiovascular disease as recommended by the Center for Disease Control and the American Heart Association." (PMID 35821205, 2022). "This local CRP levels also help to predict the risk of the development of cardiovascular diseases, which includes evidence of CRP production in cells of smooth muscle in coronary arteries in response to inflammatory cytokines." (PMID 36381804, 2022).
cardiovascular disease (continued). "In the <25 kg/m2 BMI group, age, BMI, WHtR, cardiovascular disease, MS, eGFR, hemoglobin level, albumin level, CRP level, triglyceride level, and all-cause mortality increased with TBF%, but progression to ESRD and Upcr decreased." (PMID 36185692, 2022). "Taken together, these observations suggest that there is an association between inflammaging/CRP increase and the risk of clinical cardiovascular disease." (PMID 35160156, 2022). "Both CRP and ceruloplasmin are established as markers of cardiovascular disease severity and future cardiovascular events, where ceruloplasmin has been shown to be a better predictor of long-term cardiovascular disease risk compared to CRP." (PMID 35413834, 2022). "Another CRP test called high-sensitivity CRP (hs-CRP) test was used to evaluate the risk level of future cardiovascular diseases (CVDs) as low risk (<1 μg/mL), moderate risk (1–3 μg/mL), and high risk (3–10 μg/mL)." (PMID 36551130, 2022). "Elevated CRP has also been identified as an independent predictor of pre-diabetic risk in Indians, and of cardiovascular disease in Bulgarians with IFG." (PMID 36013507, 2022). "C-reactive protein is a definitive biomarker for inflammation and has been established in clinical practice as an independent risk factor for cardiovascular disease events." (PMID 36119741, 2022). "Among apparently healthy middle-aged women baseline CRP concentration is an independent risk factor for cardiovascular disease." (PMID 36381804, 2022). "In cardiovascular disease, mendelian randomization trials strongly contradict causality and active contribution of CRP to pathogenesis." (PMID 35407379, 2022). "In the so-called “base model” (i.e., the one without including hs-cTnT and NT-proBNP) and in the one with hs-cTnT, only the history of syncope and CRP were associated with hospital admission with the diagnosis of cardiovascular disease." (PMID 35807089, 2022). "We found an association between shift work and risk factors for cardiovascular disease such as increased carotid intima media thickness and elevated C-reactive protein (CRP)." (PMID 35206173, 2022). "Chronic low‐grade inflammation is a hallmark of both cardiometabolic and cardiovascular disease and is most commonly quantified in clinical research using high‐sensitivity assays of CRP (C‐reactive protein)." (PMID 35156387, 2022). "As such, CRP has been associated with incident cardiovascular disease (CVD), including coronary heart disease (CHD), in multiple studies." (PMID 35566447, 2022). "There seems to be a linear association between CRP and cardiovascular disease, with an increased risk of 18% per 1 mg/L increase in CRP level." (PMID 36614866, 2022). "CRP acts as a marker of inflammation and numerous studies have shown that CRP is significantly associated with cardiovascular disease." (PMID 36418968, 2022). "In particular, older age, co-occurrent cardiovascular diseases, and increased C-reactive protein (CRP) levels are associated with higher risks for all-cause in-hospital mortality." (PMID 35615201, 2022). "Eighty individuals aged 70.9 ± 5.3 years were allocated to a low- (LGI) or high-grade inflammation (HGI) group based on CRP (<3 or ≥3 mg/L) as a conventional risk marker of cardiovascular diseases." (PMID 36362055, 2022). "In clinical practice, the high-sensitivity CRP (hs-CRP) test, which is more sensitive than a standard test in the region of 0.2–5 mg/L, is widely used to evaluate the risk of developing cardiovascular disease." (PMID 34439443, 2021). "The overproduction of IL-6 can increase the risk of cardiovascular diseases, with high levels of hepatic C-reactive protein (CRP)." (PMID 33815368, 2021). "The 34.0% of patients had hs-CRP levels ≥3 mg/L representative of a high risk of cardiovascular disease." (PMID 34836180, 2021).
cardiovascular disease (continued). "On the other hand, in a recent report, the presence of NH in a group of COPD patients was associated with higher serum C-reactive protein levels, a well-known risk factor for cardiovascular disease." (PMID 33573208, 2021). "More importantly, the increased plasma concentration of CRP demonstrated a specificity in predicting the risk of cardiovascular disease." (PMID 34683106, 2021). "The relationships between CRP and myocardial strain indices are reported in many cardiovascular diseases, and systemic inflammation is found to be linked to the impairment of myocardial contractility." (PMID 33745456, 2021). "Aging and high C-reactive protein levels were, usually, risk factors for cardiovascular disease mortality." (PMID 35155598, 2021). "CRP is widely used as an inflammatory biomarker in serum and associated with cardiovascular diseases at levels >10 μg/mL." (PMID 33673378, 2021). "Studies have reported that high serum concentrations of LDL-cholesterol, glucose, and C-reactive protein (CRP) are directly associated with the risk of developing cardiovascular disease." (PMID 34200914, 2021). "Mean blood C-reactive protein (CRP) levels were above the upper limit of normal (3.0 mg/L), indicative of increased risk for cardiovascular disease (mean CRP was 3.9 mg/L; SD = 8.5)." (PMID 33649360, 2021). "Linkages with CRP are important because both increases in CRP and persistently high levels of CRP are risk factors for cardiovascular disease among middle-aged and older adults." (PMID 35087386, 2021). "Such moderately elevated levels of baseline CRP, determined via high-sensitivity assays, are a predictor of cardiovascular disease, with CRP levels > 3 mg/L indicating a high risk of future cardiovascular events." (PMID 34975902, 2021). "Elevated inflammatory markers, such as high sensitivity C-reactive protein (hs-CRP), have been associated with the pathogenesis of cardiovascular disease (CVD)-related diseases." (PMID 33419190, 2021). "Individuals with more than 3.0 μg ml−1 (>3.0 ng μl−1) CRP concentrations are at high risk of cardiovascular disease." (PMID 34150714, 2021). "CRP and SAA have been linked to respiratory diseases including COPD, and CRP has also been associated with air pollution exposure and cardiovascular disease." (PMID 34863138, 2021). "CRP is an acute-phase protein that is produced by the stimulation of pro-inflammatory cytokines, which is considered a risk factor for cardiovascular diseases." (PMID 34531742, 2021). "Net reclassification index (NRI) for cardiovascular disease (generalised to a primary prevention population) with addition of information on polygenic risk scores or C-reactive protein, above conventional risk factors." (PMID 33444330, 2021). "Circulating levels of inflammatory markers, particularly C-reactive protein (CRP), are reportedly associated with cardiovascular diseases (CVDs) morbidity, as well as CVD and all-cause mortality." (PMID 34446826, 2021). "In RA patients, CRP levels have been observed to increase after acute mental stress tasks and also to be linked to risk of cardiovascular disease." (PMID 34103083, 2021). "Several studies have been reported on the association of high sensitivity CRP and cardiovascular disease." (PMID 34868746, 2021). "In the subjects that were involved in these studies, CRP concentrations were so high that they potentially increase the risk of cardiovascular disease." (PMID 33490705, 2021). "Since 2010, high sensitivity CRP (hsCRP) detection has been used clinically as a biomarker for prognosis in patients with intermediate risk of cardiovascular disease." (PMID 34408755, 2021). "In the present study, average CRP levels for the overall sample (4.30 mg/L) were high [>3 mg/L is considered high risk for cardiovascular disease] and likely reflect the age and racial diversity of the sample." (PMID 35087386, 2021).